NES (nestin)
Diseases named in the same sentence as NES in open-access papers (continued):
Sharing a sentence is not in itself a finding about the gene and the disease.
Renal cyst (1 paper, 2021). A fluid filled sac in the kidney. "An interesting question, however, is how these animals can develop a high proportion of collecting duct-derived renal cysts if nestin is not detected in ureteric bud and its derivatives nor later in collecting ducts." (PMID 34262092, 2021).
renal fibrosis (1 paper, 2014). A final common manifestation of a wide variety of chronic kidney diseases characterized by glomerulosclerosis and tubulointerstitial fibrosis. "To determine whether both pericyte subtypes accumulate after renal fibrosis, we induced UUO in Nestin-GFP/NG2-DsRed mice and evaluated fibrosis by hematoxylin and eosin, Van Gieson, and Masson’s trichrome staining." (PMID 25376879, 2014).
retinitis (1 paper, 2019). Inflammation of the retina. "Since Atg5 is a key gene regulating autophagy, we bred Atg5flox/flox; Nestin-Cre mice to deeply elucidate the role of autophagy during MCMV retinitis." (PMID 31291924, 2019). "Moreover, we observed infiltration between RPE and ONL in Atg5flox/flox; Nestin-Cre mice at day 7 p.i., indicating that autophagy is associated with immune response, which contributes to the pathogenesis of MCMV retinitis." (PMID 31291924, 2019). "We used two complimentary models-autophagy regulator (rapamycin) and autophagy knockout (Atg5flox/flox; Nestin-Cre mice) to mediate autophagy and then identified the impact of autophagy on apoptosis during MCMV retinitis." (PMID 31291924, 2019).
Right ventricular hypertrophy (1 paper, 2025). In this case the right ventricle is more muscular than normal, causing a characteristic boot-shaped (coeur-en-sabot) appearance as seen on anterior- posterior chest x-rays. "SOX17 overexpression significantly reduced PH severity, as evidenced by lower right ventricular systolic pressure (RVSP) and reduced right ventricular hypertrophy, consistent with the recovered Nestin levels in lungs (columns 2 and 3)." (PMID 40766215, 2025).
sebaceous carcinoma (1 paper, 2022). "Dermal progenitors, such as cellular retinoic acid-binding protein 1 (CRABP1), were expressed at the tumor-stroma interaction site within the core of sebaceous carcinomas and CRABP1 and nestin expression was lower in sebaceous carcinoma than in benign sebaceous adenomas." (PMID 36439142, 2022).
serous ovarian carcinoma (1 paper, 2015). "In serous ovarian carcinoma, nestin was detected in 33% of the tissues and its overexpression correlated with cisplatin-based CT resistance and shorter OS." (PMID 26421614, 2015).
Sjögren syndrome (1 paper, 2011). "Surprisingly, nestin-positve cells were observed more frequently in the Sjögren syndrome, which maybe partially explained that nestin expressed only in repairing/regeneration location, but not in quiescent cells." (PMID 21655359, 2011).
skin adnexal tumours (1 paper, 2019). "Nestin was expressed in the tumour stroma of all skin adnexal tumours." (PMID 31065284, 2019). "Nestin was expressed in the TSI of all skin adnexal tumours." (PMID 31065284, 2019).
Splenomegaly (1 paper, 2020). Abnormal increased size of the spleen. "As a result, splenomegaly was only detected at the time of analysis in symptomatic control mice treated with chemotherapy only, but not in those with nestin+ cell depletion." (PMID 32966766, 2020).
squamous cell carcinoma (1 paper, 2021). A carcinoma arising from squamous epithelial cells. "CSC-like cells were established from three squamous cell carcinomas (SCC) and three adenocarcinomas (AC) of the lung and were shown to express common CSC markers such as Prominin-1, CD44-antigen, and Nestin." (PMID 33925297, 2021).
steatosis (1 paper, 2025). Increased lipid within the cytoplasm of cells. "Liver histology showed that PI3KγNest mice were largely protected from diet-induced steatosis compared to all groups, including Nestin-CRE mice." (PMID 39811649, 2025). "However, PI3KγNest mice showed reduced adiposity, steatosis, and improved insulin sensitivity also compared to Nestin-CRE mice, indicating that the metabolic phenotype of PI3KγNest mice depends on PI3Kγ deletion." (PMID 39811649, 2025). "Nestin-CRE mice showed a trend toward less severe steatosis compared to littermate WT mice, but this difference was not comparable to the almost complete protection observed in PI3KγNest mice." (PMID 39811649, 2025).
telangiectatic osteosarcoma (1 paper, 2008). "The OSA-05 cell line was repeatedly demonstrated as nestin-negative during the long-term cultivation at different passages, and this cell line was derived from the only telangiectatic osteosarcoma, in which the only rare occurrence of Nes+ cells was demonstrated." (PMID 18925963, 2008).
Thiamine deficiency (1 paper, 2018). Thiamine deficiency is a condition that occurs due to not enough thiamine (vitamin B1). "We determined that exercise-induced changes in NGF are critical for restoring waning cholinergic/nestin neurons, blunted hippocampal ACh efflux and impaired spatial behavior following thiamine deficiency." (PMID 30443202, 2018).
thyroid cancer (1 paper, 2017). "There is an expansion of the CSC population in ATC compared to well-differentiated thyroid cancers with intense expression of the markers CD133, CD44 and nestin." (PMID 29383121, 2017).
tongue tumor (1 paper, 2021). "As our established cell line expresses both S100 and nestin, these markers may be considered as tongue tumor markers for diagnostic and therapeutic options." (PMID 33507685, 2021).
Ureteral obstruction (1 paper, 2025). Obstruction of the flow of urine through the ureter. "The aim of this study was to investigate the structural and functional changes in the cardiac muscle in RCS4 induced by unilateral ureteral obstruction (UUO) and the role of nestin+ CPCs in these." (PMID 40869420, 2025).
Vestibular schwannoma (1 paper, 2015). A vestibular schwannoma (also known as acoustic neuroma, acoustic neurinoma, or acoustic neurilemoma) is a benign, usually slow-growing tumor that develops from the VIIIth cranial nerve supplying the inner ear. "Nestin was expressed in HDF-a, although the level of expression was approximately 12-fold lower (p<0.05) than in vestibular schwannoma (top left)." (PMID 26678612, 2015).
Williams syndrome (1 paper, 2018). "Co-expression of FZD9 and Nestin has been observed in neural stem progenitor, derived from patients with Williams syndrome, a developmental disorder caused by mutations in chromosome 7." (PMID 29849507, 2018).
Zinc deficiency (1 paper, 2022). A deficiency of the essential metal Zinc; an essential cofactor for many enzymes. "For example, maternal zinc deficiency in mice impaired the expression of nestin, a marker of neural stem cells, in the offspring." (PMID 36233134, 2022). "In addition, maternal zinc deficiency during pregnancy reduces nestin levels in offspring, which could cause abnormal neurogenesis in mice." (PMID 36233134, 2022).
tumor (537 papers, 2006 to 2026). "Previous studies have linked nestin to endothelial activation during tissue regeneration and tumor angiogenesis." (PMID 40149541, 2025). "A multitude of studies have discovered that neural stem cell marker-nestin plays a critical role in regulating CSCs, and closely associates with poorer tumor grading and prognosis." (PMID 40799240, 2025). "Nestin, an intermediate filament protein typically expressed in stem cells and some malignant tumor cells, is associated with the malignant characteristics of ESCC when highly expressed." (PMID 39944625, 2025). "The study summarizes for the first time the association between tumor expression of nestin and patient survival outcomes in patients with DTC." (PMID 37485559, 2023). "Other studies reported that nestin was highly expressed in vessels and associated with tumor angiogenesis." (PMID 37735673, 2023). "Pooled results showed that higher expression of nestin (positive) in tumor was associated with worse OS (HR: 1.38, 95% CI: 1.11 to 1.72, P = .004, I2 = 68%) in patients with DTCs." (PMID 37485559, 2023). "SHH ligands secreted by tumor-associated astrocytes promote Nestin expression in SHH-MB tumor cells, an enhancer of the hedgehog signaling pathway and MB tumor growth." (PMID 36291792, 2022). "Meanwhile, Nestin expression was closely associated with malignancies, including tumor proliferation and metastasis." (PMID 34772403, 2021). "In fact, the increased expression of nestin in these tumours was associated with an immature stem-cell like phenotype, chemoresistance and enhanced capacity for invasiveness." (PMID 35008260, 2021). "Although overall nestin expression does not seem to be correlated with survival (since in this study all the patients with malignant tumors had died during the large follow-up period), tumor relapsing is associated with nestin staining." (PMID 33805026, 2021). "Nestin positivity was observed in eight of the thirty (26.7%) samples (in tumor cells, vascular endothelial cells, and fibroblasts in the tumor stroma) and was significantly associated with a high Ki-67 LI." (PMID 34943921, 2021). "Nestin expression in tumor tissue has been associated with the degree of tumor differentiation and proliferation, the invasive and metastatic capacities of tumors and/or the degree of neoangiogenesis." (PMID 34943921, 2021). "Nestin positivity was associated with poor tumor differentiation and/or an increased proliferation index, and was an unfavorable prognostic marker for ADCs." (PMID 34943921, 2021). "Expression of nestin in cancer cells is reportedly associated with the malignant phenotypes, such as tumor growth, invasion and chemotherapy resistance." (PMID 32903755, 2020). "Apart from participation in the angiogenesis of wound healing and tissue repair in various normal tissues, nestin expression has also been implicated in tumor angiogenesis." (PMID 32467665, 2020). "Various studies have shed light on the molecular mechanisms underlying the contributions of Nestin to tumor progression in vivo and in vitro." (PMID 31695040, 2019). "Taken together, our results indicate that Nestin regulates the stability of lamin A/C by protecting it from Cdk5-dependent proteasomal degradation, and Nestin deficiency can drive tumor cell senescence." (PMID 30190500, 2018). "Patients with Nestin protein expression in tumour cells more often had BRCA1 germline mutations (OR 8.7, p < 0.0005, Series III), especially among younger patients (<40 years at diagnosis) (OR 16.5, p = 0.003)." (PMID 28439082, 2017). "Much evidence has been reported that nestin expression in vascular endothelial cells is associated with neo-angiogenesis in development, tissue repair, and tumor progression." (PMID 28464921, 2017). "Gene expression signalling pathways linked to high Nestin were explored, and revealed associations with stem-like tumour features." (PMID 28439082, 2017).
tumor (continued). "Nestin expression was associated with high-grade tumour features and reduced survival by multivariate analysis, also when including the triple negative profile." (PMID 28439082, 2017). "The decreased tumour volume was associated with a reduction in the staining of SOX2 and NESTIN-positive cells, overall proliferation and viability that was accompanied by a diminution in tumour vascularization." (PMID 29053791, 2017). "When including basic clinico-pathological factors, i.e. tumour diameter, histological grade and lymph node status in multivariate analysis, Nestin expression was independently associated with reduced survival (HR, hazard ratio = 2.0, p = 0.035)." (PMID 28439082, 2017). "Previous studies have shown that CD133 and Sox2 are exclusively expressed at perinecrotic and perivascular regions associated with stem-like cell pools, and that nestin and Musashi-1 are homogeneously expressed across the tumor, identifying precursors." (PMID 28412969, 2017). "Taken together, these findings support an association between Nestin, stemness and mesenchymal tumour features." (PMID 28439082, 2017). "Generally, expression of Nestin has been detected in repair processes and in various neoplasms and has been associated with immature and angiogenic blood vessels including proliferating vascular endothelial cells." (PMID 26880936, 2016). "The results have been correlated to cell's malignancy by evaluating their co-localization with nestin, a marker associated to tumor aggressiveness." (PMID 27014421, 2016). "Both the intermediate filament protein nestin and the tumor cell-associated N-glycoprotein periostin were expressed in the cytosol." (PMID 26421614, 2015). "The present study clarified that nestin expression in tumor cells was associated with progression-free survival, cancer-specific survival, and overall survival of the patients with UCB." (PMID 24785714, 2014). "We also investigated possible association of nestin with tumor cells apoptosis by examining the expression of CDK5 and P35 using immunohistochemistry." (PMID 24966803, 2014). "Generally, expression of the intermediate filament protein Nestin has been detected in repair processes and in various neoplasms and has been associated with immature and angiogenic blood vessels including proliferating vascular endothelial cells." (PMID 25019063, 2014). "Taken together, our results imply that aberrant expression of β-catenin in astrocytic gliomas is linked to a higher tumor grade and coincides with the expression of the stemness marker nestin." (PMID 22919349, 2012). "In MGs, nestin, a marker for MgSCs, is often associated with more malignant forms of the tumour." (PMID 39316249, 2025). "Overexpression of cytoplasmic and perinuclear SOX10 may indicate its inactive form, mutated, or interacting with other proteins, such as nestin, and therefore, playing a role of greater tumor aggressiveness in oral canine melanomas." (PMID 41012776, 2025). "Additionally, a Genetically Engineered Mouse Model (GEMM) expressing the H3.3G34R mutation and ATRX loss in Nestin + progenitor cells in neonatal mice generated tumours expressing early neuronal markers Stmn2, Nefm and Nefl." (PMID 40986124, 2025). "Overall, the astrocytes play a trophic role of MB TME as they secrete the ligand sonic hedgehog (SHH) and this factor triggers the expression of nestin in MB cells; the elimination of MB-associated astrocytes led to suppression of nestin expression, blocking the tumor growth." (PMID 40677711, 2025). "Immunofluorescence of brain tissue revealed extensive localization of DiD-labeled R-EVs, accompanied by increased expression of stem cell markers (SOX2, Nestin) and the Ki67 proliferation marker in the tumor region and associated statistics indicated the Ki67, SOX2 and Nestin area to DAPI (%)." (PMID 40093910, 2025).
tumor (continued). "Nestin positivity and high expression level showed significant associations with aggressive tumor parameters such as high grade (P=0.011 and 0.008), wider tumor extension (P=0.001 and 0.011), advanced stage (P=0.017 and 0.001), higher MVD (P=0.05 and 0.026) and metastasis (P=0.045 and 0.013)." (PMID 39687450, 2024). "In addition, a significant association was observed between Nestin positivity and large tumor size (P=0.001)." (PMID 39687450, 2024). "Variables confounding the association between tumor expression of nestin and survival of DTCs may exist." (PMID 37485559, 2023). "Besides, pooled results of 6 studies showed that higher expression of nestin (positive) in tumor was associated with worse DFS in patients with DTCs (HR: 1.48, 95% CI: 1.12 to 1.96, P = .005, I2 = 56%)." (PMID 37485559, 2023). "Not only Nestin expression is significantly overexpressed in GB, compared with other types of glioma, but its deletion in tumor cells from GB patients derived xenografts caused cell cycle blockage, finally bringing to tumor cells death." (PMID 35454156, 2022). "Further, the results revealed that the association among the Nestin–Keap1–Nrf2 pathway, tumor phenotypes, and antioxidant defenses could be regarded as a possible treatment target for GC." (PMID 34772403, 2021). "As Nrf2 expression is repressed after Nestin knockdown, we determined whether Nrf2 is associated with Nestin-mediated tumor phenotypes and the antioxidant capacity of GC cells." (PMID 34772403, 2021). "Downregulation of Nestin caused significant reductions of tumor growth and weight, whereas overexpression of Nrf2 could enhance the tumor growth of Nestin-knockdown cells." (PMID 31695040, 2019). "In addition, Nrf2 depletion inhibited the rapid tumor growth caused by Nestin upregulation, indicating that the ability of Nestin to promote NSCLC development depends on the Nrf2–ARE signaling pathway." (PMID 31695040, 2019). "Thus, elucidating the contributions of Nestin to cellular structure and function is essential for understanding the mechanisms underlying tumor pathogenesis and treatment." (PMID 30190500, 2018). "Nestin expression has been reported in different organs, especially during development and in adult organs associated with conditions of repair, or in cases of neoplasms and neovascularization." (PMID 29874225, 2018). "Since tumor cell senescence caused by Nestin depletion was associated with alteration of nuclear shape, we speculated whether Nestin plays a role in maintaining the nuclear architecture." (PMID 30190500, 2018). "NES, a cytoskeletal intermediate filament protein, has been associated with increased migration in PCa cells, and increased NES expression correlated with high tumor grade, invasive phenotype, and predictor of poor response to therapy." (PMID 30100995, 2018). "Nestin protein expression by immunohistochemistry was consistently associated with higher histological grade (OR 2.7–14.3), larger tumours (OR 1.8–2.4, Series I-III), lymph node negativity (OR 3.3, Series III), and interval-detected compared with screening-detected tumours (OR 1.8–2.7, Series I-II)." (PMID 28439082, 2017). "However, mild or strong nestin expression was correlated with unfavorable tumor characteristics and an increased risk of recurrence." (PMID 25371063, 2015). "We cannot exclude the risk of tumor formation from the remaining NESTIN-positive NPCs." (PMID 25254338, 2014). "Nestin expression was associated with pathologic tumor stage (p = 0.006)." (PMID 24785714, 2014).